TRAV26-2 (T cell receptor alpha variable 26-2)
Description:
V region of the variable domain of T cell receptor (TR) alpha chain that participates in the antigen recognition. Alpha-beta T cell receptors are antigen specific receptors which are essential to the immune response and are present on the cell surface of T lymphocytes. Recognize peptide-major histocompatibility (MH) (pMH) complexes that are displayed by antigen presenting cells (APC), a prerequisite for efficient T cell adaptive immunity against pathogens. Binding of alpha-beta TR to pMH complex initiates TR-CD3 clustering on the cell surface and intracellular activation of LCK that phosphorylates the ITAM motifs of CD3G, CD3D, CD3E and CD247 enabling the recruitment of ZAP70. In turn ZAP70 phosphorylates LAT, which recruits numerous signaling molecules to form the LAT signalosome. The LAT signalosome propagates signal branching to three major signaling pathways, the calcium, the mitogen-activated protein kinase (MAPK) kinase and the nuclear factor NF-kappa-B (NF-kB) pathways, leading to the mobilization of transcription factors that are critical for gene expression and essential for T cell growth and differentiation. The T cell repertoire is generated in the thymus, by V-(D)-J rearrangement. This repertoire is then shaped by intrathymic selection events to generate a peripheral T cell pool of self-MH restricted, non-autoaggressive T cells. Post-thymic interaction of alpha-beta TR with the pMH complexes shapes TR structural and functional avidity.
Synonyms: TRAV262; TCRAV4S1; TCRAV26S2
Gene: T-cell receptor variable (V) gene on chromosome 14 (22,202,583 to 22,203,368, forward strand). Ensembl gene ENSG00000211812.
Subcellular location: Cell membrane
Gene Ontology:
Biological process: response to bacterium
Cellular component: plasma membrane
Homologues: Orthologues: chimpanzee TRAV26-2 (84% identical), macaque TRAV26-2 (79% identical). Paralogues in human: TRAV26-1 (64% identical), TRAV4 (50% identical), TRAV38-1 (29% identical), TRAV38-2DV8 (29% identical), TRAV20 (28% identical), TRAV39 (28% identical), TRAV1-1 (26% identical), TRAV21 (26% identical), TRAV10 (25% identical), TRAV1-2 (23% identical), TRAV13-1 (23% identical), TRAV17 (22% identical), and 11 more.